GSK3B (glycogen synthase kinase 3 beta)
Diseases named in the same sentence as GSK3B in open-access papers (continued):
Sharing a sentence is not in itself a finding about the gene and the disease.
mood disorder (continued). "We then evaluated the presence and regulatory phosphorylations of GSK3β, an enzyme that exhibits alterations in most mood disorders." (PMID 28240305, 2017). "A role for GSK3β inhibition (and the ensuing activation of the canonical Wnt pathway) in the therapeutic action of lithium in mood disorders is supported by preclinical studies." (PMID 23449817, 2012). "This may be of clinical interest as it suggests that lithium, utilised as a therapy in mood disorders, may decrease circulating retinol via its inhibition of GSK3B given that genetically predicted expression of this gene was positively associated with retinol." (PMID 38374065, 2024). "Preclinical studies have demonstrated the effects of Gsk-3β on mood disorders." (PMID 36983013, 2023). "Finally, recent data postulate the amygdala as a core structure in MDD, but little is known about GSK3β role in the amygdala in mood disorders." (PMID 36286471, 2022). "With all this evidence, GSK3β has emerged as a potential therapeutic target for mood disorders." (PMID 36286471, 2022). "However, further studies are needed to fully elucidate if the elevated activity of GSK3β is a reason or an effect of mood disorders." (PMID 32188010, 2020). "Indeed, the role of GSK-3β in mood disorder was highlighted by studies on the mechanism of actions of the established treatments lithium and valproate, which were both found to inhibit GSK-3β." (PMID 32380735, 2020). "This may be particularly relevant in relation to mood disorders since GSK3β is a key activator of cell death and other functions involved in mood disorders, hippocampal volume, glucocorticoid regulation and neuroplasticity." (PMID 30310078, 2018). "Its regulation of GSK3β hippocampal expression may have implications for chronic stress and mood disorder pathophysiology." (PMID 30310078, 2018). "Hence, GSK-3β is one of a number of key targets being explored with regards to possible new agents for circadian-related sleep-wake or mood disorders." (PMID 23521808, 2013). "This suggests that GSK3β is a nodal point in the processes of maladaptive neuronal plasticity triggered by chronic stress and is largely involved in the therapeutic effects of lithium in mood disorders." (PMID 23449817, 2012). "Lithium, an inhibitor of GSK-3β, has been widely used to treat mood disorders, implicating the role of GSK-3β in mood disorders." (PMID 38743109, 2024). "Studies have shown that VPA inhibited glycogen synthase kinase-3β (GSK3β) 152, and reduced GSK3β expression in response to VPA increased neuronal growth in the adult dentate gyrus (DG) in a rodent mood disorder model." (PMID 31673241, 2019). "Further work that explores molecular mechanisms related to the inhibition of GSK3β function and the promotion of EPO function within a mood disorder and cognition framework is highly warranted." (PMID 30310078, 2018). "In the present study, we focused on GSK-3β, another upstream signaling molecule of CREB-BDNF, because it is involved in various signaling systems, and with possible links to mood disorders." (PMID 24523822, 2014).
heart failure (38 papers, 2009 to 2025). Inability of the heart to pump blood at an adequate rate to meet tissue metabolic requirements. "Ventricular asynchrony in heart failure is associated with reduced Ca2+ sensitivity of myofilament proteins, and enhancing the activation energy of glycogen synthase kinase-3β (GSK-3β) improves this diminished reactivity, thereby enhancing contractile function." (PMID 40867518, 2025). "Studies have also shown that systemic inhibition of GSK3β may cause abnormal hypertrophic growth of the heart, possibly leading to heart failure." (PMID 37274326, 2023). "There is also increased levels of GSK-3β in DFUs, however, current molecules such as Thiazolidinediones that have inhibitory effects on GSK-3β are associated with a high risk of heart failure." (PMID 38671406, 2024). "On the other hand, GSK3β hypomorphic mice are protected from dilated cardiomyopathy and heart failure." (PMID 34381779, 2021). "GSK-3β is a downstream target of Akt-1 and Akt-1 which via the phosphorylation of GSK-3β can promote the survival of chronically stressed cardiomyocytes in heart failure as demonstrated by previous works." (PMID 33564362, 2021). "We then analyzed if phosphorylation of GSK3β is altered in experimental heart failure model in mice." (PMID 34948382, 2021). "Data showed that inhibition of glycogen synthase kinase 3 beta(GSK-3β) during heart failure is protective." (PMID 34322525, 2021). "Meanwhile, quercetin can also treat heart failure by upregulating the expression of GSK3β factor and cAMP and inhibiting the expression of the NF-kappa B signaling pathway." (PMID 33273955, 2020). "On the contrary, inhibition of GSK3β or overexpression of Dvl-1leads to augmented hypertrophy, severe systolic and diastolic dysfunction and progressive heart failure, in a pressure overload rat model and in transgenic mice, respectively." (PMID 28948000, 2017). "Human data suggest that downregulation of GSK-3β in the setting of hypertrophy may serve as a compensatory mechanism in early heart failure stages; however, prolonged suppression can lead to maladaptive remodeling and scar formation." (PMID 40710791, 2025). "The chemical inhibition of Gsk3b in HDAC-2 deficient mice rendered them to become sensitive to hypertrophic stimulation; thus, HDAC2 and Gsk3b may be potential targets in heart failure." (PMID 39596076, 2024). "In heart failure, salidroside can inhibit protein phosphorylation in PI3K/AKT/GSK3β pathway and protein expression of collagen-I (Col-I) and profilin-I (profilin-I) in cardiac tissue of heart failure rats, thus reducing the level of cardiac fibrosis and heart failure." (PMID 35265260, 2022). "Indeed, in heart from patients who have developed heart failure, Akt activation and consequent GSK3β inhibition seem to protect cardiac cells from apoptosis." (PMID 28948000, 2017). "Therefore, inhibition of GSK3β is an important mechanism contributing to the development of cardiac dysfunction and heart failure." (PMID 26918336, 2016). "Identification of molecular targets involved in the activation of JNKs and GSK-3β following β-AR stimulation and understanding how these kinases activate mitochondrial death pathway may provide new targets for prevention of heart failure." (PMID 21776383, 2011). "This suggests that the pharmaceutical targeting of GSK3B for the therapy of ICM in heart failure patients may also be a reasonable possibility, but more work is needed to determine the validity of this approach." (PMID 19629191, 2009). "Recent evidence from pressure overload-induced heart failure models indicates that pharmacological agents such as carnosol not only prevent ventricular arrhythmias but also mitigate adverse remodeling by modulating downstream targets of Akt, including Sirt1 and GSK-3β." (PMID 40710791, 2025).
heart failure (continued). "For instance, the STIM1 protein was observed to be present in reduced quantities in individuals with UP, and prior research indicates that silencing of Stim1 augments the activity of the anti-hypertrophic and pro-apoptotic molecule GSK-3β, which may accelerate the progression towards heart failure." (PMID 38577622, 2024). "This has prompted the development of newer GSK-3β-selective compounds such as tideglusib and 9-ING-41, which are currently being evaluated in oncology and neurology but remain untested in heart failure." (PMID 40710791, 2025). "Neutralization of Orai3 inhibits protective GSK3β phosphorylation, impairs EACH and accelerates heart failure." (PMID 30988334, 2019). "In a guinea pig model of heart failure, the S-nitrosylation levels of GSK-3β increased as the disease progressed, with S-nitrosylation-mediated inhibition eventually surpassing phosphorylation-induced activation of GSK-3β in the final stages." (PMID 40867518, 2025). "Animal experiments on Kaempferol have shown that Kaempferol can treat heart failure by inhibiting the MAPK signaling pathway, NF-kappa B signaling pathway, and PI3KAkt signaling pathway, activating the VEGF signaling pathway and upregulating the expression of GSK3β." (PMID 33273955, 2020).
renal fibrosis (37 papers, 2015 to 2026). A final common manifestation of a wide variety of chronic kidney diseases characterized by glomerulosclerosis and tubulointerstitial fibrosis. "Cross-talk between GSK3β and the Wnt/β-catenin pathway has been implicated in the development of renal fibrosis." (PMID 40526103, 2025). "The phosphorylation of GSK-3β (ser9) can inhibit its enzymatic activity and suppress the degradation of β-catenin, which causes epithelial-mesenchymal transformation, renal fibrosis, and tight junction destruction characterized by the down-regulation of E-cadherin." (PMID 35392552, 2022). "Furthermore, we demonstrated that Arrb2−/− mice exhibited resistance to IR-induced renal fibrosis and renal function impairment following chronic alcohol exposure, and these effects were associated with attenuated GSK3β activation in the kidneys." (PMID 28642577, 2017). "Proteomic screening and validation studies demonstrated that DcR2 mediated tubular cell cycle arrest through the GSK3b/cyclin D1 signalling axis, contributing to renal fibrosis following AKI." (PMID 40845179, 2025). "Pharmacological targeting of GSK3β with selective inhibitors has shown promise in preclinical models, by reducing kidney injury, attenuating renal fibrosis, and promoting renal recovery, positioning GSK3β as a potential therapeutic target for CKD." (PMID 40526103, 2025). "In vitro and in vivo experiments show that Renalase inhibits renal fibrosis by suppressing the GSK-3β/Snail signaling pathway by reducing ER stress." (PMID 39451219, 2024). "Lithium, as a GSK-3β inhibitor, can over-activate the Wnt/β-catenin pathway, thereby promoting the development of renal fibrosis." (PMID 39234304, 2024). "Proximal tubule-specific GSK-3β gene deletion can significantly reduce tubular injury, accelerate regeneration, and suppress renal fibrosis following acute kidney injury in mouse models." (PMID 36854759, 2023). "The glycogen synthase kinase-3β (GSK-3β)/Snail pathway regulates renal fibrosis and Renalase can ameliorate renal interstitial fibrosis." (PMID 37082730, 2023). "After overexpression of GSK-3β, the anti-fibrosis effect of Renalase was counteracted, indicating that Renalase inhibited renal fibrosis by inhibiting GSK-3β." (PMID 37082730, 2023). "When Renalase was overexpressed through an adenovirus, renal fibrosis was alleviated and ER stress and GSK-3β/Snail expression were also significantly decreased." (PMID 37082730, 2023). "The amelioration of renal fibrosis by Renalase and its inhibitory effect on GSK-3β/Snail were reversed by an ER stress agonist." (PMID 37082730, 2023). "Collectively, our results confirmed that Renalase can slow the progression of renal fibrosis by inhibiting ER stress and then downregulating GSK-3β/Snail signaling." (PMID 37082730, 2023). "For example, fingolimod can repress renal fibrosis by inhibiting myofibroblast production and extracellular matrix synthesis by activating GSK-3β in a UUO model." (PMID 37082730, 2023). "This indicated that Renalase regulates the expression of GSK-3β/Snail by inhibiting ER stress to improve renal fibrosis." (PMID 37082730, 2023). "We presume that SR decoction ameliorated renal fibrosis dependent on a blockade of the GSK-3β/β-Catenin signaling pathway." (PMID 35392552, 2022). "For example, the proinflammatory cysteine-rich protein 61 (Cyr61), which is increased in a mouse model of renal fibrosis, induced the phosphorylation of IκBα and GSK3B in our experimental setup." (PMID 35806457, 2022). "GSK3β inhibition by lithium has been shown to effectively ameliorate renal fibrosis in FA nephropathy mice." (PMID 36225562, 2022). "Glycogen synthase kinase 3β (GSK3β) is a serine/threonine-protein kinase that inhibits the CREB activities while promoting CBP binding to Smad3 to facilitate renal fibrosis." (PMID 35541902, 2022).
renal fibrosis (continued). "We observed increased levels of p-Tau and p-GSK3β and elevated glomerular pathology, renal dysfunction, renal fibrosis, foot process effacement, macrophage infiltration, and podocyte specific protein loss." (PMID 35368760, 2022). "Collectively, GSK3β is likely a pragmatic therapeutic target for averting profibrogenic plasticity of TECs and improving renal fibrosis." (PMID 33931588, 2021). "The inhibition of GSK-3β attenuates the process of pulmonary fibrosis or renal fibrosis, while increasing myocardial fibrosis." (PMID 34940783, 2021). "Our findings suggest that dapagliflozin ameliorates renal fibrosis by inhibiting RIP1-RIP3-MLKL-mediated necroinflammation via Wnt3α/β-catenin/GSK-3β signaling in UUO." (PMID 35069210, 2021). "Taken together, GSK-3β is closely related to the occurrence and development of renal fibrosis by affecting EMT and metabolic function." (PMID 33052244, 2020). "In the UUO mouse model, fingolimod (FTY720) downregulates the levels of α-SMA and collagen, prevents the formation of myofibroblasts, and reduces the synthesis of ECM protein by activating GSK-3β to repress the progression of renal fibrosis." (PMID 33052244, 2020). "Treatment of diabetic nephropathy mice with zinc upregulates GSK-3β phosphorylation, resulting in a reduction in the export of Nrf2 to the cytosol, thereby ameliorating renal fibrosis." (PMID 33052244, 2020). "Knockout of AKT prevents UUO-induced EMT and renal fibrosis by increasing GSK-3β activity and decreasing SNAIL and β-Catenin expression." (PMID 33052244, 2020). "In this study, we investigated the potential role of SB‐216763, a GSK3β inhibitor, in treating salt‐sensitive hypertension, and renal fibrosis." (PMID 29600538, 2018). "Given that β-arrestin 2 is critical in the regulation of GSK3 activation, which is involved in IR-induced renal fibrosis, we determined the effect of chronic alcohol treatment on the protein levels of β-arrestin 2, Akt, pAkt (Thr308), GSK3β and pGSK3β (Ser 9)." (PMID 28642577, 2017). "Using a mouse model of renal fibrosis induced by ischemia-reperfusion injury, we demonstrate increased GSK3β expression and activity in fibrotic kidneys, and its presence in myofibroblasts in addition to tubular epithelial cells." (PMID 26092126, 2015). "To determine the role of GSK3β in the development of renal fibrosis, we first examined its expression and activation in the kidneys of mice subjected to bilateral renal I/R." (PMID 26092126, 2015). "In the current studies we examined the role of GSK3β in the development of renal fibrosis and tested the effect of pharmacological inhibition of GSK3 in an I/R-induced mouse model of renal fibrosis." (PMID 26092126, 2015). "However, in some studies, elevated HIF-1α showed benefits, and pretreatment of roxadustat reduced renal fibrosis through the Akt/GSK-3β/Nrf2 pathway." (PMID 40040789, 2025). "It has been suggested that enhancing GSK3β activity may serve as a nephroprotective strategy to prevent renal fibrosis and mitochondrial dysfunction." (PMID 40076489, 2025). "On the other hand, inhibiting GSK-3β can alleviate renal fibrosis." (PMID 37082730, 2023). "What role GSK-3β plays in renal fibrosis remains to be further studied." (PMID 37082730, 2023). "On the one hand, activation of GSK-3β can improve renal fibrosis." (PMID 37082730, 2023). "GSK-3β plays a critical role in fibroblast differentiation and renal fibrosis." (PMID 36854759, 2023). "Finally, we explored the regulatory relationship between ER stress and GSK-3β/snail in the amelioration of renal fibrosis by Renalase." (PMID 37082730, 2023). "Noticeably, GSK-3β/β-Catenin is pivotal for the formation of renal fibrosis." (PMID 35392552, 2022). "Here, we demonstrated chronic METH exposure may increase p-GSK3β and p-Tau levels and lead to glomerulopathy, renal dysfunction, renal fibrosis, and podocyte pathology." (PMID 35368760, 2022).
renal fibrosis (continued). "The enhancement of GSK3β-dependent lysosome biogenesis to rebalance the ECM may be a novel strategy to counteract renal fibrosis, and LM49 may be a viable clinical candidate for treating this disorder." (PMID 36225562, 2022). "Therefore, LM49 is a potential agent to mitigate renal fibrosis by therapeutically targeting of GSK-3β." (PMID 36225562, 2022). "Additionally, the treatment of mice with chronic alcohol activates GSK-3β and aggravates renal fibrosis and function impairment." (PMID 33052244, 2020). "Therefore, our results suggest that the therapeutic targeting for Nrf2-HO-1 signaling attenuates the progression of renal fibrosis associated with diabetic nephropathy, which is manifested by the PI3K/Akt/GSK-3β pathway." (PMID 31467925, 2019). "In addition, inhibiting GSK3β may effectively slow the progression from AKI to CKD by mitigating renal fibrosis." (PMID 40526103, 2025). "Furthermore, when an adeno-associated virus or plasmid was used to overexpress GSK-3β, the effect of Renalase on delaying renal fibrosis was counteracted, although ER stress markers did not change." (PMID 37082730, 2023). "Similarly, recent findings of GSK-3β action in renal fibrosis are controversial." (PMID 37082730, 2023). "However, it is unclear whether GSK3β is expressed in renal myofibroblasts, the major producers of ECM, or whether GSK3β is involved in the development of renal fibrosis." (PMID 26092126, 2015). "Additional recent evidence demonstrates that inhibition of GSK3β enhances transcription factor EB -mediated lysosomal synthesis and facilitates ECM degradation, thereby improving renal fibrosis." (PMID 40526103, 2025). "CXCR4 was recently found to be primarily upregulated in tubular epithelial cells in renal fibrosis model and promoted kidney fibrosis by activating JAK/STAT/GSK3β/β‐catenin pathway, as reported by our previous work." (PMID 38213100, 2024). "To further clarify the role of GSK-3β/Snail in Renalase inhibition of renal fibrosis in UUO model mice, we overexpressed and knocked down GSK-3β." (PMID 37082730, 2023). "When ER stress was activated or GSK-3β was overexpressed, the effect of Renalase on UUO-induced renal fibrosis was counteracted." (PMID 37082730, 2023). "The primary pathology of the CRF model is renal fibrosis, related to the abnormal changes of several signal pathways, such as TGF-β1/Smad, MAPK signaling, and GSK-3β/β-Catenin." (PMID 35392552, 2022). "In TGF-β1-treated renal TECs, the inhibition of GSK3β can enhance the activity of CBP recruitment to CREB and thus ameliorates renal fibrosis." (PMID 35541902, 2022). "Our findings suggest that therapeutic targeting of GSK3β is likely a pragmatic approach to avert the maladaptive plasticity of renal TEC in progressive CKD and mitigate renal fibrosis." (PMID 33931588, 2021). "GSK3β inhibition intercepts the TGF-β1/Smad signaling activity that drives molecular changes of TEC profibrogenic plasticity and ameliorates renal fibrosis in CKD." (PMID 33931588, 2021). "The present work showed that GSK3β expression was amplified in renal tubular cells in patients with progressive CKD, as well as in both in vitro and in vivo models of renal fibrosis, concomitant with renal TEC fibrogenic plasticity." (PMID 33931588, 2021). "However, in renal fibrosis, Wnt molecules bind to cell membrane surface receptors, disrupting the formation of the APC-Axin-GSK-3β complex." (PMID 39325739, 2024). "GSK3β modulates the competition between CREB signalling and TGF-β1/Smad signalling for the recruitment of the shared transcriptional coactivator CBP to drive molecular changes of TEC profibrogenic plasticity and ameliorate renal fibrosis." (PMID 36225562, 2022). "Similarly, a number of publications have demonstrated that emodin retarded renal fibrosis by modulating several pathways, such as TGF-β/Smad, TGF-β/BMP-7, PI3K/Akt/GSK-3β, and Bax/caspase-3 signaling pathways." (PMID 35002735, 2021).